IFNAR1 (interferon alpha and beta receptor subunit 1)
Diseases named in the same sentence as IFNAR1 in open-access papers (continued):
Sharing a sentence is not in itself a finding about the gene and the disease.
infection (continued). "To test whether mRNA expression of hACE2 would allow the detection of infectious virus output, we followed a similar protocol to the one we had used in the adaptive immune studies where we administered 10 μg of the hACE2 mRNA or control GFP mRNA to Ifnar1-/- mice one day prior to infection." (PMID 33326500, 2020). "Moreover, naive and infected Ifnar1Δ/Δ versus Ifnar1+/+ animals displayed comparable abundances of immune-cell-related transcripts, suggesting only minor differences of immune cell infiltration between the genotypes at this early time point after infection." (PMID 31784108, 2019). "Importantly, in IFNAR1 deficient cells IL-36β no longer protected against infection and IL-36β did not induce Mx1 expression either." (PMID 31619669, 2019). "P. berghei NK65 infection in Tlr4- and Ifnar1-deficient nonpregnant females." (PMID 29440369, 2018). "However, even this abortive infection was sufficient to protect fetuses after subsequent anti-Ifnar1 antibody treatment and ZIKV challenge during pregnancy (at E10 or E11), as judged by the markedly decreased ZIKV RNA burden in feto-placental units three days after challenge." (PMID 30384472, 2018). "Our results showing that TLR4 and IFNAR1 in the placenta have fetus-protective roles reveal an unexpected outcome of the action of innate receptors that opposes the effects of maternal receptor counterparts and thereby expose a maternal-fetal conflict in the response to infection." (PMID 29440369, 2018). "The protective immunity of the VLPs in vivo and the potential of the VLPs to induce antibody-dependent enhancement of infection (ADE) will be investigated further in a suitable animal model, e.g., A129 (type I interferon receptor-deficient) or wild-type mice treated with an anti-IFNAR1 antibody." (PMID 29774519, 2018). "As type I IFNs have been described to rescue activated or memory T cells from apoptosis and to increase the longevity of these cells, we considered the possibility that IFN-β−/− and IFNAR1−/− might only show a phenotype during secondary infection with L. major." (PMID 29459858, 2018). "In contrast, type I IFNs are required for control of viremia and cellular tropism in West Nile virus infection, as infection of Ifnar1−/− mice results in a rapidly fatal infection associated with high viremia, a phenotype recapitulated in mice specifically lacking Ifnar1 only in myeloid cells." (PMID 29361691, 2018). "Furthermore, the downregulation of Ifnar1 expression in infected placentas and in trophoblasts exposed to infected erythrocytes indicated that the interferon-IFNAR1 pathway is involved in the trophoblast response to infection." (PMID 29440369, 2018). "However, in relation to MRSA-only infections of WT and Ifnar1−/− mice, treatment with exogenous IL-13 of MRSA-only infected WT mice reduced bacterial burden within 24 h, but it did not affect the ability to clear MRSA from lungs of MRSA-only-infected Ifnar1−/− mice." (PMID 27143388, 2016). "Although basal transcription of Ifnγ, S100A9 and Lcn2 was similar between mock-infected WT and mock-infected Ifnar1-/- mice, the transcription of Ifnγ and Lcn2 was significantly higher in the ceca of the Ifnar1-/- group, compared to the WT group, after infection with S. Typhimurium alone." (PMID 27149619, 2016). "To better understand how type I IFN signaling may negatively regulate bacterial clearance during L. monocytogenes infection we set out to identify those transcripts, which temporally differed between WT and Ifnar1-/- at days 1, 2 and 3 post infection, using a two-step filtering process." (PMID 26918359, 2016). "Indeed, intra-gastric inoculation of adult Ifnar1-/- mice with the human reovirus type 3 Dearing strain led to severe neurological symptoms such as hind limb paralysis, and all Ifnar1-/- animals had to be sacrificed by day 4 post-infection." (PMID 25849543, 2015).
infection (continued). "Similarly, we observed that deficiency of IFNAR1 markedly affected infection with a mixed MCMV inoculum but did not markedly affect Δm157 selection." (PMID 26720279, 2015). "Importantly, the lack of ISG induction in IFNAR1/IL28Rα deficient epithelia has biologic consequences as it leads to significantly higher virus titers at later points during infection." (PMID 24278020, 2013). "Interestingly, at a dose of 105 Ca colony-forming units (cfus) the lack of IFNAR1 caused a remarkable protection to otherwise lethal infections, which became apparent after one week of injection." (PMID 22911155, 2012). "Therefore, our results suggest that increased internalization of IFNAR1 following hMPV infection might result from the degradation of Tyk2, which is ligand-independent." (PMID 21949722, 2011). "Building upon this foundational work, our study involved the infection of Balb/c, C57BL/6J, and IFNAR1-KO mice through various methodologies to compare clinical manifestations, organ viral loads, and histopathological alterations among the infected subjects." (PMID 40733627, 2025). "In DENV-infected K562 cells, delayed expression of TLR3 and IFNAR1 was observed, accompanied by a progressive increase in IFN-β secretion, which reached its peak concentration three days post-infection." (PMID 41303574, 2025). "The Sankey diagram of IFN and receptor genes showed that Type I interferon (IFN-α) and its receptor genes (IFNAR1 and IFNAR2), Type II interferon (IFN-γ) and its receptor gene (IFNGR) were upregulated post-infection." (PMID 40469055, 2025). "Some genes were significantly different at 24 hpi with EBOVΔVP30 infection (ATG, CTSS, IFNAR1); however, the differences in expression were small." (PMID 41472248, 2025). "HCV‐1b core protein increases the expression of the miRNA, miRNA decreases IFNAR1 protein and mRNA levels, HCV‐1b infection increases miRNA levels and inhibits the IFN signaling pathway." (PMID 39185567, 2025). "Depletion of Tollip impaired IFNAR1 and IFNGR1 downregulation, most evidently at 24 and 36 hours post-infection." (PMID 40558091, 2025). "We found that STING dimers were still formed in HSV-1(F)-infected, IFNAR1 KD cells, and these dimers were exocytosed during HSV-1(F) infection." (PMID 38470056, 2024). "Using single-cell RNA-sequencing (scRNA-seq), we measured the expression of either type I (Ifnar1 and Ifnar2) or type III (Ifnlr1 and Il10rb) IFN receptor subunits in mouse lung cells on day 1 post-infection." (PMID 38530032, 2024). "CD163+Erg2+ M2 macrophages were reduced on day 1 post-infection in WT and Ifnlr1−/− mice but present in Ifnar1−/− mice, suggesting type I IFN drives depletion of M2 macrophages early post-infection." (PMID 38530032, 2024). "GSIB4+ basal epithelial cell upregulation during infection appeared to be both type I and III IFN-dependent, as this phenotype was lost in Ifnar1−/− and Ifnlr1−/− mice." (PMID 38530032, 2024). "During the initial phase, hyper-response to IFN-I due to triplication of IFNAR1 and IFNAR2 sensitizes the cells to an antiviral state, resulting in reduced infection by influenza A virus." (PMID 38540156, 2024). "To create an environment that more closely mimicked LCMV infection, with greater RRV infection and antigen in the DLN, we locally administered a blocking anti-IFNAR1 antibody at the time of infection." (PMID 39535221, 2024). "Second, we blocked IFNAR1 with anti-IFNAR1, exposed cells to EVs derived from HSV-1(F)-infected or uninfected cells, and determined their ability to restrict HSV-1(F) infection." (PMID 38470056, 2024).
infection (continued). "We administered the blocking mAb locally in the footpad at the time of infection using a nonlethal dose (6 mg/kg) to limit the systemic effects of anti-IFNAR1 treatment, including RRV dissemination to the brain and fatal infection." (PMID 39535221, 2024). "Single-nucleotide variants in the IFNAR1 and IFNAR2 genes potentially affect the immune response, exacerbate, or attenuate the disease in the face of SARS-CoV-2 infection, in addition, could be new targets for therapies that limit the infection and the resulting inflammation." (PMID 38003785, 2023). "In contrast, GSK 872 treatment significantly blunted infection-induced upregulation of IFN receptor subunits, including the type I IFN receptor subunits Ifnar1 and Ifnar2, and the type II IFN receptor subunits Ifngr1, and Infgr2." (PMID 38011306, 2023). "While 80-90% of Ifnar1-/- mice succumb to MHV68 infection following a high dose intranasal infection (4x106 PFU), ~50% survive low dose infection (4x103 PFU), with viral titers in the lungs being 100-1000 fold higher in KO mice at both high and low doses." (PMID 37065193, 2023). "One day prior to infection, C57BL/6J mice were injected intraperitoneally with a saturating dose (i.e., 2 mg) of the IFNAR1-blocking monoclonal antibody MAR1-5A3." (PMID 37112795, 2023). "During Vesicular Stomatitis Virus (VSV) and Hepatitis C Virus (HCV) infection, the specific activation of PERK favors viral replication by degrading type I IFN receptor, IFNAR1, and suppressing IFN signaling and antiviral effect." (PMID 36851680, 2023). "Following infection with an HIV-1–based reporter virus, single clones of PK-15 Ifnar1 k/o or PK-15 Stat2 k/o cells were assessed." (PMID 37939052, 2023). "The amount of virus used for infection also had a large modifying influence, with increasing MOI leading to a more pronounced proliferation advantage for IFNAR1-disrupted cells." (PMID 36909579, 2023). "Similar to STAT1-/- or IFNAR1-/- mice, STAT2-/- mice display excessive inflammation, viral burden, and increased morbidity after infection with influenza virus." (PMID 36148221, 2022). "Thus, certain organ manifestations in SLE may relate to local IFNAR1 activation, e.g., in the skin, the synovium, central nervous system, kidneys and blood vessels, either due to infection, UV light (in skin), or plasmacytoid dendritic cell migration to these sites." (PMID 36119023, 2022). "During PR8 and WSN infection, much less induction of XAF1 was observed in the Ifnar1−/− PMs than in the wide-type (WT) cells." (PMID 35972291, 2022). "Using A549 wild-type (WT), IFNAR1 knockout (KO), IFNLR1 KO, and IFNAR1-IFNLR1 double-KO cell lines, we found that both IFN-β and IFN-λ are necessary for maximum protection against subsequent infection." (PMID 36326278, 2022). "In this study, we examined the regulatory roles of IRF1, IRF7, and IFN-β in DTMUV replication and the expression profiles of infection-induced genes by constructing two knockout cell lines, KO IRF7 and KO IFNAR1, using CRISPR/Cas9 technology." (PMID 35891486, 2022). "To investigate how alterations in the interferon signaling pathway affect the cellular response to infection in the chicken, we used CRISPR/Cas9 to generate a chicken cell line that lacks a functional the type I interferon receptor (IFNAR1)." (PMID 35056582, 2022). "That is, increased amounts of IFN-1 improve anti-parasite responses by increasing IFNAR1 signalling in the early stages of infection, while exacerbated IFN-1/IFNAR1 signalling later in infection raises vulnerability to severe infection." (PMID 36081516, 2022). "In this context, where the host efficiently controls virus replication and spread, Ifnar1-/- and WT CD8 and CD4 T cells responded similarly to the infection as determined by CFSE dilution." (PMID 34015056, 2021). "Infection status contributed only ~9% to the overall variance, with PCA failing to distinguish infected from uninfected Mavs-/- mice (all of the infected Ifnar1-/- mice were females)." (PMID 34591933, 2021).
infection (continued). "We infected Ifnar-/- mice with MA-CCHFV and found that male and female Ifnar1-/- mice infected with MA-CCHFV rapidly lost weight and succumbed to the infection with a mean-time-to-death (MTD) of day 6 and day 3 PI, respectively." (PMID 33416494, 2021). "While allowing for the IFNAR1 to be maintained, a brief inhibition of the signalling allows ZIKV to replicate resulting in robust infection as compared to its untreated counterparts." (PMID 34410903, 2021). "In line with less FA import into the mitochondria in Ifnar1-/-, Seahorse flux analysis demonstrated that infection induced an enhancement in OXPHOS in all genotypes, however, Ifnar1-/- macrophages had lower OXPHOS than wt before and after infection." (PMID 34237114, 2021). "Following infection at P5/6 with ZIKV PE243 (19 mice; six litters), seven infected and six mock‐infected Ifnar1 knockout littermates (two independent litters) were culled at 4 dpi without overt clinical signs." (PMID 33942402, 2021). "While we did see increased basal H2O2 levels in Ifnar1-/- iBMDMs compared to WT, and a significant reduction in H2O2 after infection with a high dose of Bc, these infection-based differences disappeared when H2O2 levels were normalized to uninfected cells." (PMID 33684179, 2021). "The expression of type I (IFNAR1 and IFNAR2) and II (IFNGR1) receptors were suppressed in VSV-infected cells compared to mock-infection." (PMID 34578166, 2021). "Since the WT ZIKV infectious clone is attenuated in wild-type mice, we compared acute infection with X1, WT ZIKV, or the original clinical isolate PRVABC59 in adult Ifnar1−/− mice." (PMID 33080971, 2020). "Upon day 2 of infection, P. berghei ANKA induced the upregulation of the IL-12p35 and IL-12p40 genes, which was blocked by LDV coinfection but rescued in Ifnar1 KO mice." (PMID 32265335, 2020). "Apl-miR-455-5p and apl-miR-499-3p which targeted IFNAR1, plus novel-m0213-5p which targeted IFNAR2 were significantly down-regulated after DHAV-3 infection." (PMID 32019511, 2020). "We observed a trending increase in the levels of IFNAR1 and STAT1 following IFN-β treatment, similar to our findings in the adult brain following infection." (PMID 32457247, 2020). "Expression of chemokines involved in immune cell recruitment to tissue sites of infection, CCL5, CXCL10, CXCL9, and IL-15, were significantly lower in lung tissues of HTNV-infected Ifnar1-/- animals compared to WT controls." (PMID 32330200, 2020). "In this study, we found that FCV 2280 infection blocks the IFN-β-induced activation of the JAK-STAT pathway by directly and selectively degrading IFNAR1 mRNA." (PMID 33075108, 2020). "After 21 and 84 days of infection, mice were sacrificed, and lungs, spleen and serum samples were collected aseptically for analysis of IFN-β and IFNAR1." (PMID 31801478, 2019). "We chose this infection model to unravel the impact of the fetus-derived innate immunity receptors TLR4 and IFNAR1 on severe outcomes of MiP." (PMID 29440369, 2018). "IFNAR1−/− mice were infected with ZIKV-MY or ZIKV-Natal at E12.5 of gestation, and viremias were determined daily for five days post-infection." (PMID 30282919, 2018). "Infection activated PERK and increased ligand and Jak-independent phosphorylation of IFNAR1, resulting in IFNAR1 ubiquitination and degradation." (PMID 29472925, 2018). "Our data did not support this, however, as HSPCs and HSCs were more proliferative in Ifnar1-/- mice, exhibiting enhanced incorporation of BrdU during IOE infection, relative to WT mice." (PMID 30080899, 2018). "Upon intraperitoneal (i.p.)infection with a contemporary Asian strain of ZIKV (GZ01, 105 PFU/mouse), all Ifnar1−/− mice developed sustained viremia, with peak titers at 3 days post-infection (dpi)." (PMID 30333476, 2018).
infection (continued). "In an infection model utilizing immunocompetent C57BL/6 mice that were immunized and then treated with a blocking anti-IFNAR-1 antibody immediately before ZIKV challenge, 100% of Ad4-prM-E and Ad5-prM-E vaccinated mice survived." (PMID 30573745, 2018). "Using a mouse infection system displaying severe MiP outcomes, we found that the expressions of TLR4 and IFNAR1 in the maternal compartment take part in deleterious MiP outcomes, but their fetal counterparts patently counteract these effects." (PMID 29440369, 2018). "Ifnar1 is one of the subunits of the type I IFN receptor which mediates type I IFN responses in innate and acquired immunity to infection." (PMID 29112952, 2017). "Consistent with lower levels of intrahepatic viral RNA in both eHAV- and HAV-infected Tim1−/−Ifnar1−/− versus Ifnar1−/− animals, serum ALT activities were also lower in Tim1−/−Ifnar1−/− mice 7 and 14 days after infection." (PMID 28874468, 2017). "Additional Ifnar1 deficiency in Ifngr−/− mice further impaired survival suggesting that type I IFN signaling played a non-redundant protective role relatively early during infection with M. tuberculosis H37Rv and BTB 02-171 that was only apparent in the absence of IFN-γ signaling." (PMID 29230217, 2017). "Conversely, the expression of IFNAR1 and IFNGR1 was either unchanged by infection or downregulated with time, respectively, indicative of plasticity in regulating the type I IFN response and a disengagement of the type II IFN response." (PMID 28993767, 2017). "In Ifnar1 KO cultures, 4% (n = 3) and 12% (n = 3) of DAPI +ve nuclei were pyknotic at 24 hpi and 72 hpi following infection with ZIKV with an MOI of 0.3 and 3.0, respectively, compared to 3% (n = 3) in mock-infected controls." (PMID 28645311, 2017). "Following infection with RVFV, the percentages of IFNAR1-positive leukocytes increased dramatically in the blood, spleen and liver of BALB/c mice." (PMID 28769107, 2017). "Infectious RRV was present in 100% (6/6) of MLN from NOD and NOD.IFNAR1−/− mice on day 3 post infection, with virus titers 8-fold higher in NOD.IFNAR1−/− mice." (PMID 27405244, 2016). "Together, these data indicate that virus-specific CD8 T cells in CD11c-Ifnar1-/- mice are maintained at higher frequencies and remain functional during persistent CW3 infection." (PMID 27327515, 2016). "However, unlike Ifnar1-/- mice, these lineage-specific Ifnar1 deficient mice survive CW3 infection." (PMID 27327515, 2016). "MHC I levels increased at days 5 and 7 post infection on B cells in MLN of NOD and NOD.IFNAR1−/− mice." (PMID 27405244, 2016). "Although pDC CD80 levels were unaltered on day 5 post infection in MLN and PLN of RRV-infected NOD.IFNAR1−/− mice, pDC expression of MHC I was elevated in MLN and PLN." (PMID 27405244, 2016). "In addition increased levels of Ip10, Irf1, Stat1, Icsbp, at day 1 post infection in the blood of Ifnar1-/- as compared to the WT mice is in keeping with type I IFN inhibition of Th1 responses and could explain the subsequent reduction in bacterial load in the Ifnar1-/- infected mice." (PMID 26918359, 2016). "Following 24 h of infection with H5N1-tyEng91 or H5N1-tyTR05 virus, members of JAK-STAT signalling pathway (JAK1, IFN-α receptor 1 [IFNAR1], STAT-3 and protein inhibitor of activated STAT 2 [PIAS2]) were down-regulated in chicken cells." (PMID 25431115, 2014). "We previously reported that HCV-infection induces endoplasmic reticulum (ER) stress and autophagy response that selectively down regulates the type I IFN-α receptor-1 (IFNAR1) and RBV transporters (CNT1 and ENT1), leading to IFN-α/RBV resistance." (PMID 25265476, 2014). "Also in accordance with this hypothesis, extensively discussed by us in a previous work, doubly MyD88/TRIF-deficient (as MyD88/IFNAR1 DKO) mice are more sensitive to infection and do not control parasitemia." (PMID 22496959, 2012).